DKK1 (dickkopf Wnt signaling pathway inhibitor 1)
Diseases named in the same sentence as DKK1 in open-access papers (continued):
Sharing a sentence is not in itself a finding about the gene and the disease.
hepatocellular carcinoma (continued). "However, paradoxically, DKK-1 has been found to be over expressed in hepatoblastoma and hepatocellular carcinoma, suggesting that DKK-1 may be feedback regulated by activated Wnt signaling pathway." (PMID 24612589, 2014). "Additionally, high DKK1 expression correlates with poor prognosis in hepatocellular carcinoma." (PMID 21949788, 2011). "This is not so surprising because several studies have revealed that both DKK1 and β-catenin could be abundantly detected in a variety of human cancers such as chondrosarcoma and hepatocellular carcinoma (HCC)." (PMID 37108841, 2023). "Molecularly, it was shown that EZH2 silences Wnt antagonists, such as DKK1 and AXIN2, leading to Wnt/β-catenin signaling activation in hepatocellular carcinoma." (PMID 37175580, 2023). "Moreover, the co-expression of DKK1 and CKAP4 is associated with hepatocellular carcinoma (HCC) invasion and poor prognosis." (PMID 37835450, 2023). "Bmi1 and DKK1 are highly expressed in liver samples taken by biopsy from patients with hepatitis B virus‐related hepatocellular carcinoma (HCC), but the effect of both Bmi1 and DKK1 on the carcinogenesis of adult hepatic stem cells (oval cells) has not previously been reported." (PMID 33639034, 2021). "Dickkopf-1 (DKK1), an inhibitor of the most frequently impaired signaling pathway in hepatocellular carcinoma (HCC), the Wnt/beta-catenin pathway, seems to fulfill contradictory functions in the process of tumorigenesis, acting either as an oncogenic promoter of metastasis or as a tumor suppressor." (PMID 31568519, 2019). "In contrast, DKK1 is reported to be overexpressed in many malignant tissues including breast cancer, lung and esophageal carcinomas, multiple myeloma, hepatocellular carcinoma (HCC), and osteosarcoma." (PMID 25144498, 2014). "DKK1 is upregulated in some kinds of human tumors including NSCLC, hepatocellular carcinoma, pancreatic cancer." (PMID 24391982, 2013). "In hepatocellular carcinoma, all three types of IFNs are found to induce apoptosis by inhibiting β-catenin signaling pathway via a STAT3- and DKK1-dependent pathway." (PMID 23056571, 2012). "Niu and colleagues showed that EGF-receptor-(EGFR)-mediated-signaling induced DKK1-expression in hepatocellular carcinoma cells, thereby creating a negative feedback loop on sensitized cells." (PMID 37532804, 2023). "The cytotoxicity assay revealed that DKK1 was not cytotoxic towards hepatocellular carcinoma cell lines at any concentration tested." (PMID 31568519, 2019).
prostate carcinoma (58 papers, 2007 to 2026). A carcinoma that arises from epithelial cells of the prostate gland. "In prostate cancer, DKK1–4 genetic mutations are rare in primary and metastatic prostate cancer patients (0–0.68% incidence)." (PMID 35204808, 2022). "DKK1 protein overexpression has been observed in serum and advanced prostate cancer tissue specimens and is associated with poor prognosis, increased tumor growth, immune evasion, and bone metastasis." (PMID 35204808, 2022). "Our study for the first time determined the role of PRKDC as an interacting protein associated with the tumor suppressor ZBTB38 to promote DKK1 expression in prostate cancer." (PMID 34697293, 2021). "DKK1 expression is directly linked to the production of osteolytic lesions in animal models of metastatic breast and prostate cancers." (PMID 34685470, 2021). "DKK-1 expression is elevated in prostate cancer tissue compared to benign tissue and seems to be associated with worse survival." (PMID 32640686, 2020). "The Wnt inhibitor Dickkopf-1 (DKK-1) has been associated with the occurrence of bone metastases in osteotropic prostate cancer by inhibiting osteoblastogenesis." (PMID 26913608, 2016). "In conclusion, high levels of serum DKK-1 were associated with a poorer overall survival in prostate cancer patient." (PMID 25182503, 2014). "High levels of DKK-1 expression in metastatic prostate cancer tissue have been previously associated with a poorer survival." (PMID 25182503, 2014). "Mice containing one wild type and one null allele of Dkk1 exhibit increased bone mass, whereas over-expression of DKK1 has been associated with osteolytic metastatic bone disease in prostate carcinoma and MM." (PMID 17971207, 2007). "Although increased serum DKK1 seemed to be an early event in prostate cancer, which declines as cancer progresses, high DKK1 levels were associated with shorter overall survival suggesting that DKK1 could serve as a cancer prognostic marker." (PMID 27367730, 2016). "High DKK-1 serum levels are associated with a poor survival in patients with prostate cancer." (PMID 25182503, 2014). "Conversely, prostate cancer cells initially produce DKK-1 to enhance osteolytic invasion, but its expression later decreases." (PMID 40426987, 2025). "Primary immune cells were co-cultured with PC3 human prostate cancer cells in the presence of Wnt, DKK1, or immune stimulators." (PMID 40394415, 2025). "Recent DKK1 studies in prostate cancer have also demonstrated that tumor suppression can be independent of canonical Wnt signaling." (PMID 40394415, 2025). "To assess the contribution of NK cells to DKK1-mediated tumor growth in vivo, we used the DKK1-expressing human prostate cancer cell line PC3 in a severe combined immunodeficient (SCID) mouse model." (PMID 40394415, 2025). "DKK1 expression is elevated in early-stage prostate cancer, with a decrease in DKK1 levels observed in advanced bone metastases." (PMID 40002869, 2025). "In prostate cancer, the pro-cancer effect of DKK-1 is related to increased bone metastasis growth and decreased bone induction." (PMID 38376441, 2024). "Another study demonstrated that tumors of metastatic castration-resistant prostate cancer with high DKK1 expression exhibited a CD8+ T cell-poor TME infiltrated by immature M0 and M2 macrophages." (PMID 38376441, 2024). "DKK1 is a secreted protein that is a prognostic biomarker for multiple cancers, including prostate cancer." (PMID 38396744, 2024). "Our study also shows that sialic acid blockade can significantly suppress the secretion of both VEGF and DKK-1 by prostate cancer cells." (PMID 37847613, 2023). "In in vitro models, conditioned media from prostate cancer cells decreases the expression of sclerostin and DKK-1 in osteocytes." (PMID 37174109, 2023).
prostate carcinoma (continued). "In prostate cancer, which typically forms osteoblastic lesions characterized by high bone formation, the levels of sclerostin, or DKK-1, can vary during disease progression, adding complexity to our understanding of the role of osteocytes in this process." (PMID 37174109, 2023). "Other researchers have reported a co-regulation between RANKL and DKK-1 expression in different diseases, such as prostate cancer, osteosarcoma, and in children with 21-hydroxylase deficiency on chronic glucocorticoid treatment." (PMID 35237949, 2022). "Conversely, DKK1 homozygous deletion in prostate cancer is predicted to increase Wnt/β-catenin signaling via stabilization of FZD/LRP receptors at the plasma membrane." (PMID 35204808, 2022). "A phase 1b/IIa parallel-arm study of the DKK1 inhibitor DKN-01 as monotherapy or in combination with docetaxel in advanced prostate cancer with elevated DKK-1 is ongoing (NCT03837353)." (PMID 35892678, 2022). "DKK4 appears to play a similar role to DKK1 to antagonize the Wnt/β-catenin pathway, and relative to all other DKK family members, genetic variants in DKK4 are more common in prostate cancer." (PMID 35204808, 2022). "Multivariate analysis defined high serum DKK-1 levels as an independent prognostic marker for prostate cancer." (PMID 35892678, 2022). "The analysis of prostate cancer immune cells revealed that DKK1 expression levels correlated with features of immunosuppression, including increased M2 macrophages, decreased CD8+ T cells, and lower levels of activated NK cells." (PMID 35892678, 2022). "In primary prostate cancer, a strong positive correlation of S-DKK1 levels and tissue DKK1 expression levels within the tumor was reported in the past." (PMID 34638464, 2021). "Some results indicate that DKK1 expresses highly in prostate cancer tissues and promotes cancer cells proliferation and migration." (PMID 34697293, 2021). "Ace-1-Dkk-1, a canine prostate cancer (PCa) cell line overexpressing Dkk-1, was used to investigate Wnt signaling pathways in PCa tumor growth." (PMID 34437475, 2021). "Noggin and DKK1 synergistically inhibited osteoblast differentiation induced by the prostate cancer cell-conditioned media." (PMID 34685470, 2021). "By contrast, the down-regulation of DKK-1 correlates with a delay in the development of bone metastases in prostate cancer." (PMID 32640686, 2020). "They found that osteocytes modify their phenotype and show decreased expression of sclerostin and increased levels of DKK-1 in the presence of conditionally reprogrammed primary human prostate cancer cells." (PMID 32640686, 2020). "With the addition of DKK-1 and Noggin (antagonist of BMPs) to the conditioned medium, the activity of prostate cancer-induced osteoblast differentiation was diminished." (PMID 31137764, 2019). "DKK1 is a WNT signaling inhibitor and has been associated with poor survival in prostate cancer patients." (PMID 31434336, 2019). "In silico analysis to map the function of these secreted factors identified PAPPA, IGFBP2, DKK1, and TGFβ1, which have documented effects on “invasion of tumor cells” or “prostate cancer and tumors”." (PMID 29088840, 2017). "In line with previous results, we confirmed increased DKK-1 expression levels in prostate cancer tissue by analyzing a cDNA array." (PMID 26913608, 2016). "This is in contrast to those prostate cancer cell lines that mainly form osteoblastic and mixed lesions in vivo, and express low levels of DKK-1." (PMID 26913608, 2016). "It had been demonstrated that elevated DKK1 expression was an early event in prostate cancer (PCa), but during PCa progression, DKK1 expression declined, particularly in advanced bone metastases." (PMID 26799283, 2016). "In summary, the p38 MAPK isoform, MAPK11 correlates with DKK-1 expression in different stages of prostate cancer and is the main p38 MAPK isoform regulating DKK-1 expression in osteolytic prostate cancer cells in vitro." (PMID 26913608, 2016).
prostate carcinoma (continued). "We show here that the activation of p38 MAPK signaling using anisomycin also mediates an increased DKK-1 expression in prostate cancer cell lines, which normally have low levels of DKK-1." (PMID 26913608, 2016). "This suppression of DKK-1 by p38 MAPK inhibitors was also apparent in another prostate cancer cell line, DU145." (PMID 26913608, 2016). "P38 MAPKs were also increased in prostate cancer tissues compared with normal controls and furthermore, a correlation between p38 MAPKs and DKK-1 was evident." (PMID 26913608, 2016). "We next assessed DKK-1 serum levels in 80 prostate cancer patients that were available from patients included on the TMA." (PMID 25182503, 2014). "High levels of DKK-1 promoted tumour progression, and inhibition of DKK-1 decreased tumour burden in prostate cancer." (PMID 25182503, 2014). "Silencing of DKK-1 delayed the development of bone lesions in a model of prostate cancer, and neutralizing DKK-1 antibodies have been successfully applied to prevent bone lesions in a preclinical model of myeloma bone disease." (PMID 24528599, 2014). "This concept is supported by the finding that overexpression of DKK-1 in osteoblastic prostate cancer cells induces an osteolytic phenotype." (PMID 24528599, 2014). "DKK-1 tissue expression has been described to increase in primary prostate cancer lesions compared to normal tissue, and high DKK-1 levels within prostate cancer metastases were associated with poor survival." (PMID 25182503, 2014). "In line with earlier reports in prostate cancer, we show an increased DKK-1 expression in prostate cancer tissue compared to BPH." (PMID 25182503, 2014). "In prostate cancer, DKK-1 expression increases in early stages while decreasing during progression towards metastatic disease." (PMID 24528599, 2014). "By contrast, knock-down of DKK-1 delayed the development of both soft tissue and osseous prostate cancer lesions." (PMID 25182503, 2014). "Multivariate analyses defined high serum levels of DKK-1 as an independent prognostic marker in prostate cancer (HR 3.73; 95%CI 1.44-9.66, p = 0.007)." (PMID 25182503, 2014). "Here, we assessed the role of DKK-1 expression in tissues and sera from patients with prostate cancer and evaluated its prognostic value in affected patients." (PMID 25182503, 2014). "The up-regulation of DKK-1 is an early event in prostate cancer (PCa) development, thus we investigated its role as a marker in the diagnosis and prognosis of PCa." (PMID 24655661, 2014). "Moreover, a decrease of DKK1 serum level in patients with advanced prostate cancer has been reported to be associated with occurrence of osteoblastic lesions which suggests that DKK1 inhibition in PC3c cells may contribute to the osteoblastic phenotype induced by these cells." (PMID 24069383, 2013). "Wnt-3a, Wnt-5a and conditioned medium from prostate cancer cells induced osteoblast differentiation in-vitro and pretreatment of prostate cancer cells with DKK1 diminished osteoblast differentiation." (PMID 22325146, 2012). "According to the evidence, WNT released from metastatic prostate cancer cells can stimulate osteoblasts and promote tumor growth, while Dickkopf-1 (DKK1), which inhibits WNT signaling, can lead to osteolysis, particularly in the early stages of cancer development." (PMID 40002869, 2025). "DKK1 mRNA expression was higher in brain, central nervous system, head and neck, pancreatic, lung, esophageal, and liver cancers, but lower in bladder and prostate cancers." (PMID 38376441, 2024). "Dkk1 and Kremen expression in combination may act as indicators of the osteoblastic response to breast and prostate cancer bone metastases in cancer cells." (PMID 37123533, 2023). "Elevated DKK1 expression was also observed in prostate cancer, and it could be an indicator of poor survival in prostate cancer patients." (PMID 37835450, 2023).
prostate carcinoma (continued). "Furthermore, injection of a DKK1-overexpressing prostate cancer cell line C4-2B reduces bone mineral density and, therewith, leads to the formation of osteoblastic lesions in a murine animal model." (PMID 36552843, 2022). "Accumulating data suggest that the relative increase in DKK-1 expression in prostate cancer may have direct effects on tumor proliferation and the cell cycle, while the inhibition of DKK-1 reduces the tumor burden in prostate cancer." (PMID 35892678, 2022). "Likewise, high serum DKK1 levels make DKK1 a promising biomarker in esophageal squamous cell carcinoma, gastric cancer, pancreatic cancer, prostate cancer, cholangiocarcinoma, laryngeal squamous cell carcinoma, and HCC." (PMID 35355709, 2022). "In our study, we make an investigation that ZBTB38 could interact with PRKDC to promote DKK1 expression to suppress prostate cancer cell proliferation and migration." (PMID 34697293, 2021). "Overexpression of ZBTB38 could repress the proliferation and migration of prostate cancer cells via direct promotion of DKK1 expression." (PMID 34697293, 2021). "To further validate that DKK1 could mediate the tumor suppressor role of ZBTB38 in prostate cancer cells, we then knocked down DKK1 expression in DU145 cells." (PMID 34697293, 2021). "However, some researches later showed that DKK1 expression decreases in metastasis progression in prostate cancer, despite the high expression level in early development, indicating the potential tumor suppressor effect in advanced prostate cancer." (PMID 34697293, 2021). "The role and expression pattern of DKK1 in prostate cancer are complicated." (PMID 34697293, 2021). "In the future, we will focus on the role of DKK1 in prostate cancer, which could help us understand the disease better." (PMID 34697293, 2021). "Therefore, the role and expression regulating mechanism of DKK1 in prostate cancer remain to be further studied." (PMID 34697293, 2021). "Furthermore, elevated DKK-1 expression is an early event in prostate cancer; its expression declines with tumor progression, and this effect is particularly evident in advanced bone metastases." (PMID 32640686, 2020). "In addition, osteoblast stimulation and the secretion of endothelin-1 (ET-1) by prostate cancer cells have been demonstrated to suppress Dickkopf-1 (DKK-1), which stimulates Wingless-related integration site (Wnt) signaling and osteoblast bone deposition." (PMID 32640686, 2020). "Combined Dkk1 and Krm expression in cancer cells may serve as predictive markers of the osteoblastic response of breast and prostate cancer bone metastasis." (PMID 33489867, 2020). "Here, we hypothesize that signaling of p38 MAPK regulates DKK-1 expression in prostate cancer, supporting the osteolytic phenotype by impairing osteoblastogenesis." (PMID 26913608, 2016). "We first verified that DKK-1 is overexpressed in the PC3 prostate cancer cells." (PMID 26913608, 2016). "Moreover, prostate cancer cells with a predominantly osteolytic phenotype produced sufficient amounts of DKK-1 to inhibit Wnt3a-induced osteoblastic differentiation in C2C12 cells." (PMID 26913608, 2016). "In order to ascertain whether regulation of DKK-1 by p38 MAPK has clinical relevance in human prostate cancer, a cDNA array of human prostate cancer samples was analyzed." (PMID 26913608, 2016). "Interestingly, when assessing DKK-1 serum levels in patients with prostate cancer (n = 80) compared to benign prostate hyperplasia (n = 23), we did not see a significant increase (25.3 ± 6.0 vs. 27.9 ± 12.9) in DKK-1 values." (PMID 25182503, 2014). "Furthermore, in a murine model of prostate cancer, DKK-1 stimulated subcutaneous tumour growth and bone metastasis." (PMID 25182503, 2014). "The role of DKK-1 in breast cancerand prostate cancer is less well characterized." (PMID 24528599, 2014). "The role of DKK-1 in prostate cancer, however, is less clear." (PMID 25182503, 2014).